AFP (alpha fetoprotein)
Diseases named in the same sentence as AFP in open-access papers (continued):
Sharing a sentence is not in itself a finding about the gene and the disease.
tumor (continued). "Therefore, higher positive rates of serum CEA, AFP and CA19-9 in the middle-aged patients of our present study may be a result of the higher proportion of larger tumor size, T4 status and upper third tumors in middle-aged group." (PMID 27418046, 2016). "In addition, CD146 high group were more likely to manifest high AFP level (P = 0.009), vascular invasion (P = 0.016), satellite lesions (P = 0.028), no tumor encapsulation (P = 0.019), poor tumor differentiation (P = 0.006), and higher recurrence (P < 0.001)." (PMID 26928402, 2016). "Moreover, we did not identify any correlation between mtDNA content and AFP level or tumor size (data not shown)." (PMID 27063412, 2016). "Simultaneous elevation of tumor markers (AFP and CA19-9) or tumor marker elevation (AFP or CA19-9) in discordance with enhancement pattern on CT was observed in 23 of 43 patients, which was significantly more than simultaneous elevation of tumor markers (AFP and CA19-9) alone (7/43, p = 0.000)." (PMID 26917546, 2016). "The insignificant correlation between WFA+-M2BP level and AFP or DCP values indicate that WFA+-M2BP could not be an alternative tumor marker to AFP or DCP." (PMID 27626413, 2016). "Furthermore, several imbalances were observed between the antiviral and non-antiviral groups, including tumor encapsulation, tumor differentiation, and AFP." (PMID 26992891, 2016). "Higher levels of A20 protein were significantly correlated with smaller tumor size (p = 0.007), lower TNM stage (p < 0.001), lower incidence of thrombus formation (p = 0.002), lower incidence of capsular invasion (p = 0.038), and lower levels of serum AFP (p = 0.013)." (PMID 26538215, 2015). "The clinical prognostic factors that are generally accepted as unfavorable including the presence of microscopic vascular invasion or portal vein invasion, tumor capsule absence, tumor grade, AFP, and PIVKA-II were not significantly different between the BDTT and No BDTT groups." (PMID 25674733, 2015). "Patients received a score based on how many of the three variables identified in multivariate analysis as factors of poor prognosis (absence of disappearance of arterial tumor enhancement on CE-CT, AFP ratio of >1.2, CP score elevation of ≥2 points) that they had." (PMID 26421430, 2015). "Tumor cells were positive for AFP, while original umbilical vessels were negative." (PMID 26337640, 2015). "Further analysis of the clinicopathological characteristics in 83 pairs HCC specimens showed that HRC expression significantly correlated with tumor size (P = 0.026) and metastasis (P = 0.004), but not related to other clinical characteristics, including age, sex, tumor number and AFP level." (PMID 25762622, 2015). "Patients’ characteristics, such as age, sex, and preoperative tumor therapy, tumor factors, such as the number of tumors, maximum tumor size, vascular invasion, and tumor differentiation, and serum AFP levels were not significantly different between the two groups." (PMID 26472203, 2015). "Multivariate analysis showed that the absence of disappearance of arterial tumor enhancement on CE-CT, AFP ratio of >1.2, and two or more increments in the CP score after 2 weeks of sorafenib therapy were significant and independent predictors of worse survival." (PMID 26421430, 2015). "Additionally, immuno-histology of tumors observed at week 49 shows low but detectable AFP expression suggesting liver progenitor features, but most tumor sections at 49 weeks of HF–HC–HSD were AFP negative consistent with liver adenomas." (PMID 26077675, 2015).
tumor (continued). "We can assume that the difference in PFS affected OS, and that non-normalized AFP levels reflect the subclinical intrahepatic or extrahepatic tumor burden, which may be responsible for early recurrence after treatment." (PMID 26681337, 2015). "Also the role of the serum level of AFP not always correlate with the tumor growth and it has been showed that is less useful than previously tough." (PMID 27275318, 2015). "Tumor markers (alpha fetoprotein, AFP, β-HCG, and lactate dehydrogenase, LDH) were also negative." (PMID 26576317, 2015). "However, that patient’s AFP level did not decrease, and she died due to tumor progression 4 months after ablation." (PMID 26578035, 2015). "By contrast, ANXA2 levels do not correlate with tumour size and AFP levels." (PMID 24348815, 2014). "In addition, routine laboratory tests are usually inconclusive and normal serum tumor markers, including AFP, CEA, CA199 and CA125, do not exclude other primary and secondary liver tumors." (PMID 25120715, 2014). "In the present study, lower serum albumin levels, higher AST levels, higher serum AFP levels, multinodularity, larger tumor size, the presence of vascular invasion, and noncurative treatment modalities were associated with poorer overall survival in HCC treatment." (PMID 25546689, 2014). "There are no specific clinical manifestations but tumor markers, including AFP and β-HCG, may help to detect the tumor earlier." (PMID 24396468, 2014). "The long-acting release formulation of octreotide (octreotide LAR), at a dose of 10 mg administered monthly, has been proven to be useful in the treatment of HCC, resulting in AFP levels normalization and a complete and prolonged regression of the tumour in a patient with not resectable HCC." (PMID 25225571, 2014). "In addition, AFP levels greater than 500 ng/mL are correlated with tumor size: 80% of small HCCs show no increase in AFP concentration." (PMID 25165471, 2014). "We found that decreased PTPN12 expression was a prognostic factor for poor cancer-specific survival and recurrence-free survival of HCC patients (P<0.001) independent of serum AFP levels, tumor size, multiplicity, clinical stage and vascular invasion as evidenced by multivariate analysis." (PMID 24475046, 2014). "AFP, BCLC stage, Child-Puge class and satellite nodules were significantly associated with survival, whereas other features, including gender, age at diagnosis, tumor size, HBV, relapse and tumor multiplicity, were not." (PMID 25275448, 2014). "By immunohistochemistry, the tumor cells were positive for vimentin and α-1-antichymotrypsin; negative for cytokeratin 7 (CK7), CK19, CK8/18, hepatocyte paraffin, mucin-1, cluster of differentiation 31 (CD31), CD34 and AFP; and the positive rate of Ki67 was 80%." (PMID 25120683, 2014). "Laboratory detection of tumor markers, such as AFP, CA19-9 and CEA were usually negative." (PMID 23938157, 2013). "We can furthermore not exclude that the observed basal activity of the AFP promoter might be a indication of the tumor characteristics of all immortalized cell lines." (PMID 23734827, 2013). "Cx43 expression correlated with early tumor recurrence (P = 0.001), disease-free survival (P = 0.026), and overall survival (P = 0.000) in patients with serum AFP < 400 ng/ml, but not in those with serum AFP ≥ 400 μg/L." (PMID 23800357, 2013). "Tumor markers were measured: CEA (carcinoembryonic antigen) = 4.77 ng/mL (normal < 5 ng/mL); serum CA-125 level = 1835 IU/mL, more than 60 times above the normal superior limit (normal < 30 IU/mL); AFP (alpha-fetoprotein) = 8.1 ng/mL (normal < 20 ng/mL); ECG (electrocardiogram) was normal." (PMID 23431489, 2013). "Furthermore it is a sensible marker for tumor’s evolution; infact a rapid decrease of AFP levels in the serum after surgery is a sign of absence of residual tumor." (PMID 24251245, 2013).
tumor (continued). "Although the AFP serum level reflects the intrahepatic tumor burden, assessment of serum PIVKA-II level reflects the extent of vascular invasion, including portal vein thrombosis and extrahepatic disease extension, and is regarded as complementary to serum AFP measurement." (PMID 24455683, 2013). "Hence we conclude that PBOV1 can be classified to tumor-specific antigens (TSA), a class of genes postulated a long time ago, but the attempts to identify specific members have been mostly unproductive, with one notable exception being the alpha-fetoprotein." (PMID 23418531, 2013). "In HCC, serum AFP-L3 and Des-gamma-carboxy prothrombin (DCP) are two of the most studied alternative HCC tumor markers, and may be more effective than AFP alone in differentiating HCC from non-malignant hepatopathy and predicting prognosis." (PMID 23874805, 2013). "As the results, we found that the expression levels of GRB2 protein in HCC tissues with the higher tumor stage (T3~4) and the positive serum AFP level were significantly lower than those with the lower tumor stage (T1~2, P=0.01) and the negative serum AFP level (P=0.006), respectively." (PMID 24391994, 2013). "It was reported that to some extent, high-sensitivity AFP-L3, AFP-IgM complex, calcium, GP73, DCP bursin, VEGA, GPC-3, and other markers can improve the sensitivity for detection of tumor recurrence in AFP-negative HCC, and have predictive value for the HCC therapeutic effect." (PMID 23981851, 2013). "With the same IL-24 gene, Ad•DD3•E1A•(IL-24) or Ad•AFP•E1A•ΔE1B•(IL-24) could completely eliminate xenograft tumor, but the Ad•AFP•E1A•E1B(Δ55)•IL-24 could not, showing the importance of vector." (PMID 23675261, 2012). "Moreover, hsa_miR_16_M was simultaneously related with the most number of clinical characteristics (AFP, ALT, and 5 cancer staging indexes), which further suggested that miR-16 and its targets might correlate with invasive tumor cell behavior." (PMID 23282077, 2012). "Western blot confirmed the immunofluorescence results and that AFP expression could be detected in tumor cells but not in TAECs." (PMID 23171368, 2012). "Unfortunately, AFP serum concentrations do not correlate well with the prognostic values of HCC such as tumor size, stage, or disease progression, and ethnic variability may also exist." (PMID 22655201, 2012). "In addition, AFP levels greater than 500 ng/ml are correlated with the tumor size: 80% of small HCC show no increase of AFP concentration." (PMID 22244200, 2012). "The tumor cells were strongly positive for wide-spectrum cytokeratin, BerEP4, and alpha-fetoprotein (αFP); partially positive for CD117 (C-kit); negative for glial fibrillary acidic protein (GFAP), S-100 protein, CD30, and the beta subunit of human chorionic gonadotropin (βHCG)." (PMID 23326746, 2012). "In addition, immunohistochemically, the tumor cells of H-YSTs are positive for CK besides AFP and HepPar1, and negative for hepatocyte antigen, CK20, CEA and EMA." (PMID 21443783, 2011). "In these studies, an early stage, minimal residual tumor after the initial surgery, less than 100 cc of ascites, platinum-based chemotherapy, an AFP level less than 1,000 kU/L, and a non-EST histology were found to be significantly related to a more favorable prognosis." (PMID 21988930, 2011). "However, AFP did not significantly increase the hazard ratio of extrahepatic metastasis in any combination of tumor markers based on multivariate analysis." (PMID 21985636, 2011). "However, there was no significance between other patterns of final AFP response and tumor progression type." (PMID 20813065, 2010). "Elevated tumour marker levels can be helpful in establishing the diagnosis in patients with advanced germ cell tumours as approximately 85% of cases of OGCT make one or both of the tumour markers hCG and AFP, with a poorer prognosis for those producing both at presentation." (PMID 20587067, 2010).
tumor (continued). "Thus AFP is likely to be a marker of tumour cell de-differentiation rather than a marker of hepatic metastases from NETs." (PMID 18577995, 2008). "a) Alpha-fetoprotein mRNA (AFP mRNA) It has recently been demonstrated that AFP mRNA expression detected by reverse-transcription polymerase chain reaction (RT-PCR) in peripheral blood 1 week after surgery correlated with the recurrence of HCC and was a good predictor for tumor recurrence." (PMID 17244360, 2007). "However, diagnosing patients with small lesions, poor blood supply, and lack of abnormal serum AFP and tumor markers remains clinically challenging, and conventional imaging based on morphology cannot effectively judge the systemic invasion and biological activity of tumors." (PMID 40123907, 2025). "GPC3 elevation can be detected in about 50–60% of AFP-negative HCC patients, which may be related to its specific activation in dedifferentiated tumor cells, while elevated DCP is caused by defective carboxylation of specific amino-terminal glutamic acid residues in HCC patients." (PMID 41471145, 2025). "Additionally, relying exclusively on MRI without complementary biomarkers, such as α-Fetoprotein (AFP), may reduce comprehensive tumor characterization and impact the accuracy of outcome predictions." (PMID 41300869, 2025). "Consistently, subgroup analysis also confirmed that patients with preserved liver function (Child–Pugh class A), dominant tumor size <6 cm, low AFP (<400 ng/ml), no history of HBV and HCV infection, are men, and aged >58 years could benefit from this combination therapy." (PMID 40703528, 2025). "However, at presentation, serum tumor markers were negative (AFP 5 ng/mL and β-HCG 6 mIU/mL)." (PMID 38668041, 2024). "However, we were able to evaluate one of the criteria, namely whether the three tumor markers (AFP, DCP, ALP-L3) remained negative for 24 weeks or longer." (PMID 39451767, 2024). "Also, in the pure presentation, tumor markers such as AFP and beta-HCG are negative." (PMID 39238734, 2024). "Moreover, before PSM, there was significant heterogeneity in baseline data between the two groups, such as gender, AFP, tumor size, MVI, satellite foci, tumor number, and tumor envelope, which may be significantly different from the inclusion criteria of the two groups at the beginning of treatment." (PMID 39170098, 2024). "Interestingly, nearly half of the patients (57/117) had more than 10 tumors, indicating that if a patient expresses a low AFP level (≤ 100 ng/mL) and has tumors as large as 3 cm, a high tumor number (≥ 10) may not affect HCC recurrence." (PMID 36967432, 2023). "However, CTC count did not correlate with the largest tumor diameter or AFP." (PMID 37298294, 2023). "However, AFP is a product of tumour cells and has no biological effect on promoting tumour growth." (PMID 37024609, 2023). "Importantly, R848@M2pep-MPsAFP-reprogrammed M2-like TAMs process and present AFP antigen to CD8+ T cells with R848 as the immune adjuvant, resulting in promoted CD8+ T cell proliferation and activation as well as enhanced stem-like CD8+ T cells in tumor tissues." (PMID 37704614, 2023). "However, multiple TAAs, including AFP, were not 100% tumor-specific, and promiscuous recognition of unassociated epitopes of normal proteins might cause off-target reactivity of both therapies, which could cause serious systemic toxicity." (PMID 35002508, 2022). "In addition, DEX containing alpha-fetoprotein (AFP) can stimulate mice with HCC to produce more IFN-γ and IL-2, which was conducted by the increase of CD8+ T cells and then decreased the regulatory T cells (Tregs), IL-10, and TGF-β, improving the tumor microenvironment." (PMID 35126514, 2022). "Importantly, complete tumor eradication was observed in mice bearing large established tumors with tumor load of 0.62 ± 0.05 cm in longitudinal diameter after three repeated intravenous injections of DEXP&A&N, with greater T cell responses specific for AFP epitope." (PMID 35488312, 2022).
tumor (continued). "However, accurate clinical staging is hampered by the inability of imaging procedures to detect micro-metastatic seeds and by the non-expression of tumour markers alpha fetoprotein (AFP), beta human chorionic gonadotropin (bHCG) and lactate dehydrogenase (LDH) in almost 50% of the cases." (PMID 34775512, 2022). "However, not all HCC tumours contribute to an increase in AFP." (PMID 36590993, 2022). "Besides the major imaging features of HCC (non-rim enhancement, washout and enhancing capsule), tumor necrosis or severe ischemia (TNSI) on imaging and two clinical characteristics (gender and alpha fetoprotein) were also independently associated with HCC diagnosis (all P < 0.01)." (PMID 35761201, 2022). "Since HCC cells are surrounded with non-tumor stroma consisting of components of the extracellular matrix such as non-malignant fibroblasts and immune and endothelial cells, paracrine stimulation may exist in the development of HCC that enhances the expression of AFP." (PMID 34680245, 2021). "In addition to AFP, other serum biomarkers, such as the neutrophils-to-lymphocytes ratio (NLR), AFP-L3 and des-γ-carboxyprothrombin (DCP), resulted to be surrogate markers of tumor biology and have been considered for inclusion in pre-transplant prognostic models." (PMID 34638365, 2021). "In this study, the AFP-specific T cell response was not only found to be specific to HCC patients but was also highly distributed in patients with advanced-stage HCC, which implied that the AFP-specific T cell response might be a signature of tumour status in the advanced stage." (PMID 34496797, 2021). "Thus, when considering patient eligibility in treatment protocols for advanced HCC, liver reserve appears to be a relevant factor, whereas extrahepatic metastasis, patient age, initial tumor size, serum AFP level, and degree of portal vascular invasion are not." (PMID 34440985, 2021). "Interestingly, Subdoligranulum showed a negative correlation with tumor marker alpha-fetoprotein." (PMID 34239449, 2021). "Consonant with this hypothesis, the administration of adiponectin (5 μg/kg weekly) blocked tumor progression in a thioacetamide-induced rat HCC model, resulting in an 80% increased survival rate, 73% reduced average number of nodules and 46% decreased serum AFP." (PMID 34064999, 2021). "In analyses correcting for lead-time in the AFP group (doubling time 120 days), the respective adjusted HRs for the AFP group were unchanged (0.74 and 0.67), but they were no longer significant after additional adjustment for tumor stage and curative treatment (0.87 and 0.81)." (PMID 32845895, 2020). "The Hangzhou criteria restrict LT for HCC patients with a total tumor size no more than eight cm in diameter, or a total tumor diameter more than eight cm with a histopathologic grade of well or moderate differentiation as well as a preoperative alpha-fetoprotein (AFP) level no more than 400 ng/mL." (PMID 32127944, 2020). "Moreover, chemerin did not correlate with AFP, tumor number or size in a recent study." (PMID 31409008, 2019). "Moreover, Kaplan-Meier analysis revealed that without received TACE (P = 0.035), high AFP level (P = 0.030), larger tumor size (P = 0.002), multiple tumor (P < 0.001), satellite nodule (P = 0.007) and vascular invasion (P < 0.001) were positively associated with shorter OS in HCC patients." (PMID 31136302, 2019). "Interestingly, our nine-gene signature was associated with OS in each subgroup significantly, regardless of age, gender, serum levels of AFP, tumor number, tumor size, tumor differentiation, except for tumor stage III/IV and the presence of microvascular invasion." (PMID 31215439, 2019). "Furthermore, 105 of liver-resident CD8+ T cells from tumor and non-tumor site of HLA-A2 restricted HCC patients (n = 5) were stimulated with IL-35 for 6 h, and were co-cultured in direct or indirect contact with 5 × 105 of HepG2 cells in the presence of AFP peptide." (PMID 31134088, 2019).